TFF3 (trefoil factor 3)
Diseases named in the same sentence as TFF3 in open-access papers (continued):
Sharing a sentence is not in itself a finding about the gene and the disease.
gastric ulcer (4 papers, 2020 to 2024). An ulcerated lesion in the mucosal surface of the stomach. "While TFF3 expression is typically challenging to detect in normal gastric mucosa, the robust expression of TFF3 can be observed in the periulcer tissues of gastric ulcer patients and rats." (PMID 38731435, 2024). "However, TFF3 expression is enhanced in the gastric mucosa and periulcer tissues of patients and rats with gastric ulcer." (PMID 35039476, 2022).
metastatic disease (4 papers, 2003 to 2025). "This might appear to contradict previous functional studies in PC cell lines (cells isolated from metastatic disease), where high TFF3 expression has been suggested to have an oncogenic role in late stage PC." (PMID 28930171, 2017). "In metastatic tumors, significant reductions were observed in DIO1 activity (11-fold), TFF3 gene expression (8-fold), TPO expression (4-fold), and SLC26A7 expression (2.6-fold)." (PMID 40650194, 2025).
adenoma (3 papers, 2004 to 2025). A neoplasm arising from the epithelium. "Among the 26 primer sets that proceeded to the second screening, only a primer set to amplify TFF3 cDNA showed a clear difference between adenomas and carcinomas." (PMID 15083192, 2004). "Five oxyphilic tumours (four adenomas and one carcinoma) showed decreased expression levels of TFF3 mRNA." (PMID 15083192, 2004). "One sequence tag that represents trefoil factor 3 (TFF3) mRNA showed a clear difference in its expression level between adenomas and carcinomas." (PMID 15083192, 2004).
Alzheimer disease (3 papers, 2016 to 2022). A progressive, neurodegenerative disease characterized by loss of function and death of nerve cells in several areas of the brain leading to loss of cognitive function such as memory and language. "In disease, TFF3 has been associated with cell growth, metastasis and angiogenesis in cancer as well as with neurodegenerative disorders such as Alzheimer's disease." (PMID 26556395, 2016). "Low TFF3 in CSF is a predictive factor for brain atrophy and its potential role in the pathogenesis of Alzheimer disease (AD) has been suggested." (PMID 29392081, 2018).
Cerebral ischemia (3 papers, 2013 to 2021). Restriction of arterial blood supply to the brain associated with insufficient oxygenation to support the metabolic requirements of the tissue. "There are two fundamental questions about the present investigation: how cerebral ischemia causes hepatic upregulation of TFF3 and how TFF3 protects ischemic neurons from irreversible injury." (PMID 24204940, 2013). "In association with TFF3 upregulation in the hepatocyte, the serum level of TFF3 was increased significantly from day 1 to 5 after cerebral ischemia/reperfusion injury as tested by ELISA." (PMID 24204940, 2013). "In this report, we demonstrate that experimental cerebral ischemia/reperfusion injury in the mouse causes upregulation of the secretory protein trefoil factor 3 (TFF3) in the hepatocyte in association with an increase in serum TFF3." (PMID 24204940, 2013). "Expression levels of genes encoding ER stress markers, oxidative stress/antioxidative enzymes and proinflammatory cytokines were determined in liver tissue from Tff3−/− and WT animals exposed to HS diet or LS diet during brain ischemia protocol." (PMID 31635131, 2019). "Intravenous administration of recombinant TFF3 reversed the change due to TFF3 deficiency, suggesting a neuroprotective role for TFF3 in cerebral ischemia/reperfusion injury." (PMID 24204940, 2013). "Here, we tested the hepatic response to experimental cerebral ischemia/reperfusion injury in the mouse, focusing on the expression of TFF3 in the hepatocyte, the contribution of the liver to the elevation of serum TFF3, and the neuroprotective action of TFF3." (PMID 24204940, 2013). "Hepatic upregulation of TFF3 in response to cerebral ischemia/reperfusion injury represents an endocrine protective mechanism." (PMID 24204940, 2013). "The present investigation demonstrated a previously unrecognized endocrine neuroprotective mechanism involving the secretory protein TFF3 upregulated in the liver in response to cerebral ischemia/reperfusion injury." (PMID 24204940, 2013). "To confirm the hepatic contribution, we tested the serum level of TFF3 in the presence of cerebral ischemia/reperfusion injury and partial hepatectomy (~60% liver resection), a model known to reduce the serum level of liver-secreted proteins." (PMID 24204940, 2013). "Here, we show that the liver also contributes to neuroprotection in cerebral ischemia/reperfusion injury by upregulating and releasing the secretory protein TFF3." (PMID 24204940, 2013). "Data on the Tff3 gene/protein role in cerebral ischemia-reperfusion injury are scarce." (PMID 31635131, 2019). "Recombinant Tff3 protein administered intravenously reversed the cerebral injury and forelimb motor function, indicating that an endocrine neuroprotective mechanism that uses liver Tff3 protein is engaged in cerebral ischemia/reperfusion injury." (PMID 31635131, 2019). "For example, a recent study demonstrated that following the myocardial and brain ischemia, mice unable to synthesize adequate quantities of the Tff3 protein in their liver lack the protective effect of the Tff3 protein in serum, resulting in greater tissue damage." (PMID 31635131, 2019). "In the cerebral ischemia/reperfusion model with severe neuronal infarction, this assay may not be used to identify differences between the wild-type and TFF3-/- mice." (PMID 24204940, 2013). "Cerebral ischemia/reperfusion injury induced upregulation of TFF3 expression in hepatocytes." (PMID 24204940, 2013). "When fluorescein-TFF3 (50 ng/g of body weight) was administered intravenously to mice with 24-hr cerebral ischemia/reperfusion injury, fluorescein-TFF3 extravasation was found in the ischemic brain tissue, but not in the intact brain tissue, within 1 hr following administration." (PMID 24204940, 2013). "Wild-type and TFF3-/- mice exhibited similar changes in the pattern and distribution of MAP2 in cerebral ischemia/reperfusion injury." (PMID 24204940, 2013).
Cerebral ischemia (continued). "Other selected organs, including the ischemic brain tissue, lung, pancreas, small intestine, kidney, and skeletal muscle, did not exhibit noticeable TFF3 upregulation in cerebral ischemia/reperfusion injury at the TFF3 peak expression time in the liver." (PMID 24204940, 2013). "To date, TFF3 has not been investigated for involvement in cerebral ischemia/reperfusion injury." (PMID 24204940, 2013).
cervical cancer (3 papers, 2017 to 2024). A primary or metastatic malignant neoplasm involving the cervix. "Here, we identify a novel candidate therapeutic target, trefoil factor 3 (TFF3) which overexpressed in cervical cancer cells and was associated with reduced postoperative survival." (PMID 28070169, 2017). "Several studies demonstrated that TFF3 overexpression strongly correlated with poor prognosis in various tumors, which indicated that TFF3 could be a potentially superior diagnostic marker or therapeutic target for cervical cancer." (PMID 28070169, 2017). "Compared with HaCaT cells, TFF3 was expressed at higher level in all the cervical cancer cell lines tested." (PMID 28070169, 2017). "As expected, the phosphorylation level of STAT3 was decreased with JSI-124 treatment in TFF3-overexpressing cervical cancer cells." (PMID 28070169, 2017). "In this study we demonstrated that TFF3 functionally promoted the malignant progression of cervical cancer cells." (PMID 28070169, 2017). "Our data suggested that TFF3 stimulated an invasive phenotype in cervical cancer cells through STAT3 mediated repression of CDH1." (PMID 28070169, 2017). "Considering the rapid changes in proliferative and molecular patterns of expression associated with the oncogenic characteristics, which indicated TFF3 plays an important role in the malignant progression of human cervical cancer." (PMID 28070169, 2017). "This study contributes to our understanding of the molecular mechanism by which overexpression of TFF3 in human cervical cancers promotes tumor progression." (PMID 28070169, 2017). "In SiHa and Hela cells, forced expression of TFF3 promoted cervical cancer cells growth, proliferation and invasion." (PMID 28070169, 2017). "By two-dimensional Matrigel Transwell analysis we found TFF3 was critical for cervical cancers to involve invasion." (PMID 28070169, 2017). "We therefore examined the behavior of cervical cancer cells with either forced or depleted expression of TFF3 growing on two-dimensional Matrigel." (PMID 28070169, 2017). "Western blot analysis showed that overexpression of TFF3 repressed E-cadherin (CDH1) expression to promote the invasion of cervical cancer cells." (PMID 28070169, 2017). "Overall, our work provides a preclinical proof that TFF3 not only contributes to the malignant progression of cervical cancers and but also is a potential therapeutic target." (PMID 28070169, 2017). "Conversely, TFF3 knockdown in two cervical cancer cell lines increased CDH1 expression mRNA level with concomitant decrease of phosphorylation of STAT3." (PMID 28070169, 2017). "But siRNA-mediated depletion of TFF3 induced the apoptosis of cervical cancer cells by decreasing anti-apoptotic protein, Bcl-2 and increasing pro-apoptotic protein, Bax." (PMID 28070169, 2017). "Conversely, TFF3 knockdown increased the sensitivity of cervical cancer cells to etoposide and promoted apoptosis." (PMID 28070169, 2017). "Functional studies demonstrated that TFF3 overexpression promoted the proliferation and invasion of cervical cancer cells, and inhibited the apoptosis by inducing the mRNA changes in SiHa and Hela cell lines." (PMID 28070169, 2017). "Conversely, TFF3 silencing disrupted the proliferation and invasion of cervical cancer cells, and induced the apoptosis via Click-iT EdU test, flow cytometry analysis and two-dimensional Matrigel Transwell analysis." (PMID 28070169, 2017). "However, in vitro studies with cervical cancer cells reported that TFF3 overexpression correlates with increased proliferation and invasion of these cells." (PMID 38396964, 2024). "To investigate whether TFF3 contributes to the proliferation of cervical cancer cells in vitro, we analyzed the proliferation upon overexpression and knockdown of TFF3 in SiHa and Hela cells." (PMID 28070169, 2017). "For the first time, we found that TFF3 was overexpressed in cervical cancer cells." (PMID 28070169, 2017).
cervical cancer (continued). "Furthermore, overexpression of TFF3 decreased the sensitivity of cervical cancer cells to etoposide by increasing P-glycoprotein (P-gp) functional activity." (PMID 28070169, 2017). "Furthermore, we found TFF3 decreased the sensitivity of cervical cancer cells to etoposide by increasing P-gp functional activity in the two cell lines." (PMID 28070169, 2017). "In order to verify whether the endogenous function of TFF3 is to promote proliferation, it was followed by knocking down cervical cancer cells expressing high level of TFF3." (PMID 28070169, 2017). "CDH1 is a downstream protein of TFF3 and may be a key modulator of TFF3-mediated cervical cancer invasion." (PMID 28070169, 2017). "In addition, TFF3 levels correlated with the proliferative potential of cervical cancer cells as revealed by correlation between TFF3 and Ki67 levels in vivo." (PMID 28070169, 2017). "Moreover, we observed that TFF3 repressed the expression of CDH1 to promote cell invasion in cervical cancer cells." (PMID 28070169, 2017). "This is supported by a recent study in which TFF3 decreased E-cadherin expression in a manner dependent on STAT3 activity, hence promoting the invasiveness of cervical cancer cells." (PMID 29100386, 2017). "In the present study, we found that TFF3 protein was overexpressed in cervical cancer cells and weakly expressed in human non-tumor keratinocytes." (PMID 28070169, 2017). "The present work first found that TFF3 was overexpressed in cervical cancer cells and weakly expressed in human non-tumor keratinocytes." (PMID 28070169, 2017). "In the cervix cells, TFF3 expression was detected significantly higher level in cervical cancer cells than in human non-tumor keratinocytes." (PMID 28070169, 2017). "Despite the evidence that TFF3 could influence various cancer cells function in vitro, the role of TFF3 in cervical cancer cells has not been examined." (PMID 28070169, 2017).
colorectal adenocarcinoma (3 papers, 2017 to 2024). The most common type of colorectal carcinoma. "To address this, we used TFF3-overexpressing colorectal adenocarcinoma cells (HT-29/B6/TFF3) as a model for scattering cancerous cells that are protected from IFN-γ/TNF-α-induced apoptosis." (PMID 28149533, 2017). "We considered TFF3-mediated resistance to apoptosis in colorectal adenocarcinoma cells as a basis for exploring RNA regulatory networks that confer the observed apoptosis-resistant phenotype." (PMID 28149533, 2017). "In trefoil factor 3 (TFF3) overexpressing colorectal adenocarcinoma cells (HT-29/B6), we observed enhanced resistance against TNF-α/interferon gamma-induced apoptosis." (PMID 28149533, 2017).
depression (3 papers, 2015 to 2022). "The current findings contribute to our understanding of the antidepressant-like effects of TFF3 and the underlying mechanisms in an established animal model of depression." (PMID 26633367, 2015). "In fact, cerebral TFF3 has been reported to be involved in several processes, such as fear, depression, and learning." (PMID 36371440, 2022). "In order to further identify the antidepressant-like effect of TFF3, we applied an olfactory bulbectomy (OB), a classic animal model of depression, in the present study." (PMID 26633367, 2015). "In summary, chronic TFF3 treatment normalized olfactory bulbectomy induced depressive-like behaviors by the regulation of the BDNF-ERK-CREB pathway in the hippocampal CA3, a brain area crucial for depression." (PMID 26633367, 2015). "Our findings further confirmed the therapeutic effect of TFF3 against depression and suggested that the normalization of the BDNF-ERK-CREB pathway was involved in the behavioral response of TFF3 for the treatment of depression." (PMID 26633367, 2015).
endometrioid carcinoma (3 papers, 2014 to 2022). "The diagnostic value of TFF1, TFF2 and TFF3 was then evaluated by immunohistochemistry on 206 stage I-II OCs stratified by histotype (high-grade serous carcinoma [HGSC], endometrioid carcinoma [EC], clear cell carcinoma [CCC], and MC)." (PMID 36818673, 2022). "TFF3 expression, ARID1A loss and beta-catenin expression had 100% specificity in diagnosing grade 3 endometrioid carcinoma, but relatively low sensitivity at 37%, 33%, and 7%, respectively." (PMID 30550483, 2019). "The presence of TFF3 staining, beta-catenin expression and loss of MMR protein expression appears useful in diagnosing grade 3 endometrioid carcinoma and these markers may be included in extended panels." (PMID 30550483, 2019).
endometrioid endometrial carcinomas (3 papers, 2008 to 2013). "Significant correlations between TFF3 over-expression and poor prognosis have been previously reported in cholangiocarcinoma and endometrioid endometrial carcinoma, which is consistent with our result." (PMID 24358147, 2013). "This study identifies the genetic fingerprint of poorly differentiated endometrioid endometrial carcinomas (G3-EEC) and analyses the potential utility of trefoil factor 3 (TFF3) as novel serum marker in G3-EEC." (PMID 18682706, 2008).
endometriosis (3 papers, 2023 to 2025). The growth of functional endometrial tissue in anatomic sites outside the uterine body. "Additionally, TFF3 has been confirmed as a high-risk gene for endometriosis." (PMID 38098472, 2023). "It revealed significantly elevated expression of MUC5B (p = 8.44E-06) and TFF3 (p = 6.41E-06) in endometriosis tissues compared to control tissues, consistent with our prior analytical findings." (PMID 40757199, 2025). "Recent research indicates that the TFF3-PAR2 inhibitor peptide effectively reduces TFF3 activity, thereby inhibiting the occurrence and progression of endometriosis." (PMID 38098472, 2023). "Regarding tissue type preference, the C0 FHL2+ Fibroblast and C2 CXCR4+ Fibroblast subpopulations were more common in Endometriomas, while the C3 RAMP1+ Fibroblast, C1 SFRP2+ Fibroblast, and C4 TFF3+ Fibroblast subpopulations were predominantly found in Endometriosis." (PMID 41159025, 2025). "Our IHC analysis identified MUC5B and TFF3 as specifically overexpressed in endometriosis." (PMID 40757199, 2025).
enteritis (3 papers, 2016 to 2024). Inflammation of the small intestine. "(2020) found that serum TFF‐3 concentrations were significantly increased in enteritis caused by various infectious agents in neonatal calves and TFF‐3 along with I‐FABP, L‐FABP and IAP were useful and reliable biomarkers in determining intestinal epithelial damage." (PMID 38648253, 2024).
enteropathy (3 papers, 2016 to 2024). "The enteropathy was associated with an extensive depletion of goblet cells indicated not only by H&E but also by the more sensitive staining of TFF3, CLCA1, and processed and unprocessed MUC2." (PMID 34237462, 2021).
follicular adenoma (3 papers, 2004 to 2013). "Using HDSS, we detected TFF3 as a differentially expressed gene between follicular adenomas and carcinomas." (PMID 15083192, 2004). "The expression of TFF3 mRNA is decreased significantly in follicular carcinomas compared with follicular adenomas." (PMID 15083192, 2004). "In follicular tumours, a significant difference in the expression levels of TFF3 mRNA was observed between follicular adenomas and carcinomas." (PMID 15083192, 2004). "In this study, by using HDSS, we screened differentially expressed genes in a follicular carcinoma and a follicular adenoma, and found a decreased expression of trefoil factor 3 (TFF3) mRNA in follicular carcinomas." (PMID 15083192, 2004). "The expression levels of TFF3 mRNA in 48 follicular adenomas and 29 follicular carcinomas were measured by real-time quantitative RT–PCR using a specific probe for TFF3." (PMID 15083192, 2004). "Thus, when an accurate system to measure the quantity of TFF3 mRNA is established, it may be possible to distinguish follicular adenomas and carcinomas preoperatively." (PMID 15083192, 2004). "In our preliminary study, differentiation of follicular adenomas from follicular carcinomas was not possible by the in situ hybridisation study since both tumour cells showed a positive staining of TFF3 mRNA (data not shown)." (PMID 15083192, 2004). "The reason for the differential expression of TFF3 in follicular adenomas and carcinomas is not clear." (PMID 15083192, 2004).
gastric tumor (3 papers, 2016 to 2021). "In contrast, Cdx2 is essential for intestinal epithelium differentiation to regulate the expression of Muc2 and Tff3, and it is upregulated during the progression of gastric tumors." (PMID 26839577, 2016). "Furthermore, previous studies have reported a negative correlation of TFF3 level and HER2 status, in which TFF3 was found to be more frequently expressed in gastric tumours without HER2 amplification as compared to those with HER2 amplification." (PMID 29088778, 2017). "Associated to mucins, too, is the family of trefoil factors, including the gastric tumor suppressors TFF1 and TTF2, which are co-localized with MUC5AC and MUC6, respectively; and TFF3, which is typically not secreted by gastric mucosa but, like MUC2, by goblet cells." (PMID 34227026, 2021).